CCNB1 (cyclin B1)
Diseases named in the same sentence as CCNB1 in open-access papers (continued):
Sharing a sentence is not in itself a finding about the gene and the disease.
cancer (continued). "The exact mechanism linking between PI3K–Akt signaling and CDK1–cyclin B1 to dictate ER–mitochondria metabolic function in cancer cell survival remains an open issue." (PMID 34064109, 2021). "The aberrant behavior of cancer cells mediated by over-expression of Cyclin B1 and D1 contributes to the accumulation of genetic lesions that will eventually result in the creation of a radioresistant and thus more aggressive tumor." (PMID 34141616, 2021). "Modulation of mitochondrial oxidative metabolism fuel to produce ATP required for cancer cell survival was related to CDK1–cyclin B1 activity." (PMID 34064109, 2021). "CCNA2 and CCNB1 are 2 members of the cyclin family, which regulate cell proliferation and apoptosis, and have been closely related to cancer progress and patients’ survival." (PMID 34596112, 2021). "CCNB1 (cyclin B1), play a pivotal role in mediating cell cycle progression (from G2 phase of cell cycle to mitosis) and metabolism reprogramming in cancer cell." (PMID 34077304, 2021). "For example, CCNB1 and AURKA were proved to be significantly associated with the prognosis of HCC and HBV-HCC and proposed as hub genes in these cancers." (PMID 33946043, 2021). "CCNB1, also known as CyclinB1, belongs to the family of highly conserved cyclins and is significantly overexpressed in various cancers." (PMID 34434217, 2021). "A seminal early study showed that FOXM1 and several of its transcriptional targets, such as AURKB and CCNB1, rank in the top 70 genes for which overexpression is associated with chromosomal instability (CIN) in pan-cancer (named the CIN70 signature)." (PMID 34205406, 2021). "It has been reported that CCNB1 shows increased expression levels throughout the cell cycle in considerable cancers includingovarian carcinoma." (PMID 35540695, 2021). "Proanthocyanidin b2 and plumbagin were the most common compounds in herbs related to TOP2A and CCNB1, showing good potential for cancer treatment including HCC." (PMID 33946043, 2021). "Overexpression of CDK1, MCM2, E2F2, PLK1, CCNB1/2, BUB1, BUB1B, CDC25 has been associated with aberrant proliferation in many cancer types including HCC." (PMID 33499054, 2021). "Accumulating studies revealed that CCNB1, CCNB2 and TOP2A are associated with the prognosis of cancer and active carcinoma pathogenesis 38-40." (PMID 32201520, 2020). "Deregulation of genes involved in the mitotic checkpoint, such as BUB3, CCNB1, and PTTG1, can contribute to cancer development by increasing the risk of incorrect cell division, aneuploidy, and genomic instability." (PMID 31801961, 2020). "Previous findings report that berberine inhibited the expression of cyclin B1 to induce G2/M phase arrest in numerous cancer types." (PMID 31991634, 2020). "TUBA1C (r was range from 0.29 to 0.66), TUBA1B (0.21~0.65), P4HA1 (0.25~0.74), HSPA8 (0.17~0.60), CCNB1 (0.22~0.62) as the top five genes were highly correlated with glycolysis score across cancers." (PMID 32635458, 2020). "CCNB1 and cytoplasmic BUB3 scores were integrated with the Cancer of the Prostate Risk assessment post-Surgical (CAPRA-S) score by adding two points for each marker if they were positive." (PMID 31801961, 2020). "Overexpression of CCNB1 resulting in cell proliferation and was reported in various cancers including NSCLC." (PMID 31681566, 2019). "Both QC and QS inhibited the proliferation and migration of primary cancer hepatocytes by reducing cyclin B1, cyclin D1 and N-cadherin expression and increasing E-cadherin expression." (PMID 30723284, 2019). "Cyclin B1, the regulatory subunit of cyclin-dependent kinase 1 (Cdk1), is another interesting target, as it is overexpressed in several cancer cells and plays a role in cancer cell survival and proliferation." (PMID 30866424, 2019).
cancer (continued). "Several studies have reported that cyclin B1 level increases in cancer cells arrested in the G2/M phase." (PMID 31554189, 2019). "Among the significant prognostic gene pairs, the gene pair CCNB1_TERT is the only prognostic gene pair shared by the three types of cancer." (PMID 31856825, 2019). "PRFR halted cancer cells proliferation by inducing the cells to arrest at the G2/M phase of the cell cycle via the down-regulation of survival proteins, cyclin B1 and cdc25." (PMID 30813458, 2019). "We found that the hub genes (BUB1B, CDC25C, CENPE, kinesin and CCNB1) make up an essential response across many cancer types." (PMID 31396397, 2019). "CCNB1 belongs to the highly conserved cyclin family and is significantly overexpressed in various cancer types." (PMID 31850229, 2019). "As a transcription factor, FOXM1 has many target genes including KIF20A, CENPF, CCNB1, MYC, NIMA-related kinase 2, MMP2, MMP9, and S-phase kinase-associated protein 2 that are implicated in cancer initiation, progression, or drug resistance." (PMID 31072351, 2019). "Cyclin B1 and cdc25 proteins are the potential candidates of the proteins involved in cell proliferation in cancer cells by inducing cell cycle progression." (PMID 30813458, 2019). "Previous studies have shown that downregulation of cyclin B1 specifically suppresses the activity of Cdk1 further leading to a strong proliferation inhibition and apoptosis induction in various cancer cells, both in vitro and in vivo." (PMID 31803360, 2019). "Another study indicated that cyclin B1 was expressed in different time-window sections of G1 in malignant cancer cells." (PMID 30965609, 2019). "Previously it has been shown that targeting Cyclin B1 inhibits proliferation and sensitizes cancer cells to taxol, and that apoptosis induced by drugs is often accompanied by the down-regulation of Cyclin B1." (PMID 31249607, 2019). "Down regulation of cyclin B1 and phosphor-cdc 2 after corilagin treatment on cancer cells was discovered." (PMID 30609707, 2019). "As expected, overexpression of CDK1, as well as high expression of its binding partner cyclin B1, has been described in many cancers with poor prognosis." (PMID 30190546, 2019). "Deregulated Cyclin-B1 expression has been observed in various cancers like esophageal squamous cell carcinoma, laryngeal squamous cell carcinoma, and colorectal cell carcinoma and induces resistance against radiotherapy in different tumors." (PMID 29861465, 2018). "Several studies have demonstrated that SFN causes G1/S and G2/M cell cycle arrest by altering the levels of cyclin A, cyclin B1, cyclin D1 and p21cip1/waf1 in cancer." (PMID 28864908, 2018). "Advanced techniques need to be developed to allow effective delivery of plasmids, such as circ-Ccnb1, into solid tumors for future cancer therapy." (PMID 29795334, 2018). "CCNB1 overexpression has been found to occur in HCC and many other cancer, often being linked to progression, recurrence, and to poor prognoses." (PMID 30245591, 2018). "Cytoplasmic overexpression of cyclin B1 has been reported in several cancers including head and neck cancers and is related with advanced histological grade and local recurrence of these cancers." (PMID 29785357, 2018). "The inevitable role of cyclin-B1 in abnormal cellular growth makes it a striking therapeutic target for cancer management." (PMID 29861465, 2018). "First, multiple genes already used in the clinic as cancer biomarkers encode proteins within the Src signature, including Her2, MUC16, PLAU, SERPINE1, Aurora A kinase, Cyclin B1, GRB7 and Ki-67." (PMID 29904729, 2018). "When cancer cells are treated with the inhibitor of fatty acid synthase, the increased protein expression of cyclin B1 was observed." (PMID 30388870, 2018).
cancer (continued). "It has been reported that FOXM1 enhances cancer cell growth through upregulating the cell cycle-related genes cyclin B1 and cyclin D1." (PMID 29552295, 2018). "The top five upregulated DEGs, including CDK1, CCNB1, TOP2A, MYC, and PCNA, were associated with cell mitosis and involved in the development of cancer." (PMID 30092828, 2018). "Ectopic circ-Ccnb1 decreased the proliferative capacity of cancer cells relative to vector-transfected cells." (PMID 29795334, 2018). "CCNB1 (also known as CyclinB1) serves as a vital regulator of cell cycle, which is significantly overexpressed in various cancer types." (PMID 30363964, 2018). "Elevated cyclin B1 expression levels are a common feature of various cancer models and associated with a poor prognosis for cancer patients." (PMID 29545747, 2018). "Previous studies reported that high CCNB1 expression levels were detected in various cancers such as breast, colon, and non-small cell lung cancer." (PMID 30380668, 2018). "Among these, CCNB1 (cyclin B1) is the key oncogenic driver whose overexpression itself leads to the chronic proliferation of cancer cells." (PMID 30380668, 2018). "We further examined circ-Ccnb1 expression in a number of cell lines and found that the non-cancer cell lines expressed much higher levels of circ-Ccnb1." (PMID 29795334, 2018). "We detected significantly lower levels of circ-Ccnb1 in the cancer tissues relative to the benign samples." (PMID 29795334, 2018). "In previous cancer studies, overexpression of cyclin B1 was demonstrated to correlate with adverse survival outcome, while some others showed cyclin B1 was a potential biomarker for favorable prognosis." (PMID 27903976, 2017). "Many chemotherapeutic agents and experimental/medicinal compounds inhibit growth of a variety cancer cells in part by targeting cyclin B1 and promoting G2M arrest." (PMID 29285223, 2017). "LicA treatment decreased the expression of MDM2, Cyclin B1, Cdc2 and Cdc25C in H460 and A549 cancer cell lines." (PMID 28805696, 2017). "Specifically in TNBC, inhibition of CDK9 has been linked to decreased cyclin B1 and MYC, and treatment with dinaciclib resulted in G2/M phase arrest and cancer cell apoptosis." (PMID 29137393, 2017). "Here we conducted the first systematic evaluation of the literatures with respect to cyclin B1 expression and clinical outcomes in cancer patients to date." (PMID 27903976, 2017). "A growing body of research indicates that dysregulated expression of cyclin B1 is a common event in cancer cells." (PMID 27903976, 2017). "Our previous study revealed that LCSE arrested cancer cells in the G2/M phase by reducing the expression of cyclin B1." (PMID 28056952, 2017). "The mitotic kinase Cdk1/Cyclin B1 is involved in regulation of G2/M transition and their overexpression is predictive of poor survival and chemoresistance in human cancers." (PMID 29245943, 2017). "One of the cyclins, cyclin B1, controls the transition from the G2 to M phase of the cell cycle, and abnormal expression of this protein is widely reported in cancers." (PMID 27999202, 2017). "Cyclin B1 is a key mitotic cyclin in the G2-M phase transition of the cell cycle and is overexpressed in various malignant tumors." (PMID 27903976, 2017). "AURKA and CCNB1 are oncogenes overexpressed in many types of cancer and they are involved in progression of the cell cycle, and positively correlated with tumorigenesis, metastasis and chemotherapy resistance." (PMID 27355345, 2016).
cancer (continued). "MiR-15a/16-1 cluster within 0.5 kb at chromosome position 13q14 target several oncogenes (including BCL2, CCNE1 and CCNB1, which also existed in the two networks), to suppress cell cycle progression and proliferation in several malignant tumors." (PMID 27966444, 2016). "Another study showed that abundance of cyclin G1 increased radiosensitivity of cancer cells through activation of cyclin B1, enhanced radiosensitivity was correlated with increased cyclin B1." (PMID 27602752, 2016). "High level of CCNB1 expression has been detected in a variety of cancers, including GC, resulting in uncontrolled cell growth." (PMID 27183908, 2016). "Cyclin B1 mRNA was overexpressed in 139/150 (92.7%) pairs, with an average increased fold change of 5.30 in cancer tissues." (PMID 25962181, 2015). "Compared with the normal tissues, the acrophases of Per2 and CDK1 were earlier in precancerous lesions, and the acrophases of Cyclin D1, CDK1 and Cyclin B1 occurred later in the cancer cells." (PMID 25950458, 2015). "Accordingly, the downstream pathway targets of c-Myc as well as those of cyclins D1 and D2 (e.g. pRb, cyclin A2 and cyclin B1) were also downregulated and contributed to the anti-cancer activity of tylophorine." (PMID 25669982, 2015). "USP22 regulates CCNB1 protein stability to promote cell cycle progression, as well as cancer cell growth, when it is aberrantly upregulated." (PMID 27030811, 2015). "Elevated levels of CCNB1, in particular its nuclear accumulation, indicate more aggressive cancer and poor prognosis; however, the contributing factors remain to be identified." (PMID 27030811, 2015). "JZ534 induced the G2/M cell cycle arrest of the cancer cells and suppressed the expression of cycle-related proteins, including cyclin B1 and Cdc2." (PMID 25977922, 2015). "Cyclin B1 is responsible for the transition of the cell from the G2 to the M phase but changes to a disruption in cancer cells where overexpression of cyclin B1 can lead to uncontrolled cell growth." (PMID 26555773, 2015). "How the cancer cells proceed G2/M phase exit while maintaining high levels of Cyclin B1 for growth advantage is an unresolved interesting question." (PMID 27462423, 2015). "In this study, the expression levels of CDC20, BUB1, MCM2, and cyclin B1 were upregulated in the 3 and 10 μmol/l genistein groups, indicating the promoting effects of genistein on cancer cell proliferation." (PMID 25385471, 2015). "It does this, at least in part, by down-regulating PIWILI, cyclin B1, cyclin D1, bcl2 and up-regulating bax gene expression in several types of cancer cells, including A549." (PMID 25007054, 2014). "The expression of Erk1/2 and p38 MAP kinases, cyclin B1 and checkpoint kinase proteins (Chk1 and Chk2) in Caco-2 cancer cells were investigated following 72 h exposure to A. indicum extract." (PMID 24348703, 2013). "Previous studies showed knock-down of Cyclin B1 in cancer cell lines resulted in reduced cell proliferation." (PMID 23874748, 2013).
cancer (continued). "Currently two groups have shown the potential for miRNA-mediated regulation of Cyclin B1 in cancer cell lines." (PMID 23874748, 2013). "Survivin and cyclin B1, both involved in cell survival and proliferation and frequently deregulated in human cancers, are good candidate target genes for siRNA mediated therapeutics." (PMID 23835136, 2013). "Cyclin B1 was expressed to some extent in all normal and cancer tissues, localized either in cytoplasm or nucleus." (PMID 23722120, 2013). "More recently, the sensitivity of cancer cells to antimitotic drugs has been shown to have a dependence on the ability of cyclin B1/Cdk1 to phosphorylate and increase the degradation of Mcl-1 in order to enhance apoptosis." (PMID 24058878, 2013). "Another potential therapeutic target for cancer treatment is represented by cyclin B1, the regulatory subunit of cyclin-dependent kinase 1 (cdk1), which plays a pivotal role in the transition of the cell cycle from G2 phase to mitosis." (PMID 23835136, 2013). "Sp1, a cell growth and survival transcription factor, has been shown to associate with SUV39H1 upon hydrogen peroxide treatment in an epithelial carcinoma cell line, leading to growth arrest through the silencing of Sp1 target genes, including cyclin B1." (PMID 23705022, 2013). "The present study showed that the cells in carcinoma with aberrant nuclear localization of cyclin B1 not only pushes on cell from G2-M mitosis phase but also demonstrate lack of cell differentiation into next stratum." (PMID 23722120, 2013). "Chemotherapy agents such as taxol and etoposide induced G2/M arrest in cancer cells accompanied with the increase of cyclin B1." (PMID 19897545, 2011). "By contrast, HPV+ cancers up-regulated, relative to HPV-HNC, a much larger set of cell cycle-specific genes such as cyclin E2 (CCNE2; G1 associated), cyclin B1 (CCNB1; G2 associated), and multiple MCMs." (PMID 21447181, 2011). "Cyclin B1 expression level increases in the transition from benign through premalignant to advanced malignant breast lesions." (PMID 19293801, 2009). "CCNB1 encoding cyclin B1 and CDK1 encoding cdc2 were overexpressed, as in many cancer types, both essential components of the cell cycle regulatory machinery." (PMID 19662092, 2009). "For example, HPV-positive cancers, compared to HPV-negative, upregulated a much larger set of cell cycle-specific genes such cyclin E2 (G1 associated), cyclin B1 (G2 associated) and multiple MCMs." (PMID 19036130, 2008). "In this work, as a proof-of-concept, the RNA interference was used to downregulate/deplete cyclin B1 and a clear antiproliferative effect was observed in all cancer cell lines studied." (PMID 19113992, 2008). "Abnormal expression of CCNB1 has been observed in various cancers and inflammatory diseases." (PMID 40406126, 2025). "Indeed, several genes—such as BMYB, FOXM1, polo-like kinase 1 (PLK1), Aurora kinase A (AURKA), and CCNB1—regulated and suppressed by the DREAM complex are overexpressed in various cancers and are associated with a poor cancer prognosis." (PMID 39796178, 2025). "The timing and kinetics of cyclin B1 degradation is of crucial importance for understanding the regulation of cell division, karyotype stability and the efficiency of mitosis-targeting anti-cancer drugs." (PMID 40804104, 2025). "Consequently, researchers have developed CCNB1 inhibitors as a means to induce cell cycle arrest and trigger apoptosis specifically in cancer cells." (PMID 41439111, 2025).